MARCHF3 (membrane associated ring-CH-type finger 3)
Description:
E3 ubiquitin-protein ligase which may be involved in endosomal trafficking. E3 ubiquitin ligases accept ubiquitin from an E2 ubiquitin-conjugating enzyme in the form of a thioester and then directly transfer the ubiquitin to targeted substrates.
Synonyms: MARCH-III; MARCH3; RNF173; MGC48332
Tractability: Antibody: UniProt predicts a signal peptide or a membrane-spanning region.
Gene: Protein-coding gene on chromosome 5 (126,867,714 to 127,031,268, reverse strand). Ensembl gene ENSG00000173926.
Subcellular location: Cytoplasmic vesicle membrane; Early endosome membrane
Subcellular location (Human Protein Atlas): Vesicles
Gene Ontology:
Molecular function: protein binding; ubiquitin-protein transferase activity; ubiquitin protein ligase activity; zinc ion binding
Biological process: protein ubiquitination
Cellular component: endosome; lysosome; cytoplasmic vesicle membrane; early endosome membrane
Genetic constraint (gnomAD): Loss-of-function variants: 13 observed, 25.3 expected, observed/expected ratio (o/e) 0.51, 90% interval 0.33 to 0.82. The upper end of that interval is the gene's LOEUF score, 0.82, which puts it in group 3 of 6, group 1 being the genes least tolerant of losing a copy. Missense variants: 276 observed, 342.12 expected, observed/expected ratio (o/e) 0.81, 90% interval 0.73 to 0.89. Synonymous variants: 144 observed, 144.06 expected, observed/expected ratio (o/e) 1, 90% interval 0.87 to 1.15.
Homologues: Orthologues: chimpanzee MARCHF3 (99% identical), macaque MARCHF3 (99% identical), mouse Marchf3 (99% identical), rat Marchf3 (99% identical), dog MARCHF3 (98% identical), pig MARCHF3 (98% identical), guinea pig MARCHF3 (97% identical), tropical clawed frog marchf3 (94% identical), rabbit MARCHF3 (81% identical), zebrafish zgc:158785 (43% identical), Caenorhabditis elegans marc-3 (25% identical). Paralogues in human: MARCHF2 (64% identical), MARCHF1 (24% identical), MARCHF9 (23% identical), MARCHF4 (23% identical), MARCHF8 (23% identical), MARCHF11 (22% identical).
Diseases named in the same sentence as MARCHF3 in open-access papers:
MARCHF3 is named in the same sentence as 17 diseases in open-access papers, as found by Europe PMC text mining. Sharing a sentence is not in itself a finding about the gene and the disease.
MARCHF3 shares sentences with these, for which no sentence is quoted: tumor (3 papers); cancer (2); hepatocellular carcinoma (2); mastitis (2); adenocarcinoma (1); breast carcinoma (1); chronic hepatitis (1); fibrosarcoma (1); infection (1); liver cancer (1); liver cirrhosis (1); lung adenocarcinoma (1); lung squamous cell carcinoma (1); nonalcoholic fatty liver disease (1); ovarian carcinoma (1); pancreatic cancer (1); Sepsis (1).